P2RY12 (purinergic receptor P2Y12)
Diseases named in the same sentence as P2RY12 in open-access papers (continued):
Sharing a sentence is not in itself a finding about the gene and the disease.
depression (9 papers, 2020 to 2025). "It’s implicated that P2RY12-mediated cardiovascular thrombosis and cerebral microglia activation may provide potential targets for MI with depression, that deserves much more attention in the research of psycho-cardiology diseases." (PMID 39936089, 2025). "Since P2RY12 expression was also upregulated in this brain area following suicide in bipolar disorder (BD) and in major depressive disorder (MDD) patients, the increase in P2RY12." (PMID 38025265, 2023). "Second, we investigated depression-/anxiety-related factors in neurons, microglia, astrocytes, and oligodendrocytes in DEX-dams and found that P2ry12, which is a purinoreceptor microglia-specific gene, decreased in the hippocampus." (PMID 37396924, 2023).
asthma (8 papers, 2013 to 2023). "A recent study has suggested that the purinergic receptor P2Y12 is required for LTE4 mediated pulmonary inflammation in a mouse model of asthma and signals in response to cysLTs." (PMID 23472176, 2013).
epilepsy (8 papers, 2018 to 2023). A brain disorder characterized by episodes of abnormally increased neuronal discharge resulting in transient episodes of sensory or motor neurological dysfunction, or psychic dysfunction. "Lastly, while several purinergic receptors have been shown to modulate microglial function during epilepsy, including P2ry12 and P2rx7, we only observed significantly increased expression of P2rx4." (PMID 29925434, 2018). "Furthermore, P2RY12 genetic deletion in mice exacerbated seizure outcome associated with reduced microglial processes, suggesting a neuroprotective role of P2RY12-dependent microglial process extension in epilepsy." (PMID 33561958, 2021). "Collectively, these data suggest P2RY12 and TMEM119 are robust discriminators of microglia and TAMs in human tissue, both in epilepsy tissue and in the context of glioblastoma." (PMID 34286275, 2021). "From our staining, we determined P2RY12 and TMEM119 were the best markers for the delineation of microglia and TAMs and subsequently used these to define populations across epilepsy, meningioma, low-grade, and glioblastoma tumor tissue." (PMID 34286275, 2021). "Tissue sections from resected low-grade, meningioma, and glioblastoma (grade IV) tumors and epilepsy tissues were immunofluorescently triple-labeled for Iba1 (pan-myeloid marker), CD14 or CD163 (preferential TAM markers), and either P2RY12 or TMEM119 (microglial-specific markers)." (PMID 34286275, 2021).
melanoma (8 papers, 2013 to 2023). A malignant, usually aggressive tumor composed of atypical, neoplastic melanocytes. "Preclinical trials have shown that P2RY12 inhibitors could reduce the tumor spread in melanoma, ovarian, breast, lung, and pancreatic cancers." (PMID 34589424, 2021).
pancreatic cancer (8 papers, 2017 to 2022). "We previously demonstrated that anti-P2RY12 drugs inhibit cancer-associated-thrombosis and formation of tumor metastasis in pancreatic cancer models." (PMID 34589424, 2021). "Pancreatic cancer cells express the purinergic receptor P2Y12, that is an ADP receptor found mainly on platelets." (PMID 34858977, 2021). "Our results show that P2RY12 is not only expressed in platelets, but also in pancreatic cancer cells." (PMID 34589424, 2021). "The activation of the P2RY12 on pancreatic cancer stimulates cell migration and proliferation." (PMID 34589424, 2021). "Finally, we demonstrate that pancreatic cancer cells express the purinergic receptor P2Y12, an ADP receptor found mainly on platelets." (PMID 29064388, 2017).
viral infection (8 papers, 2018 to 2024). "The receptor encoded by P2RY12 senses a broad range of CNS insults including viral infections and drives microglia into a phagocytic state." (PMID 34052228, 2021). "While in vitro studies suggest P2RY12 may be associated with anti‐inflammatory microglia, its roles during CNS aging and viral infection are unknown." (PMID 34327802, 2021). "While P2RY12 may be diminished under inflammatory conditions, its expression is still sufficient for differentiation of infiltrating myeloid cells and microglia, even under inflammatory conditions after virus infection." (PMID 39425188, 2024). "In regions with more prolonged viral infection (i.e., the rostral region of the brain), infiltrating Ly6Chi macrophages had lower Ly6C expression and higher expression of CX3CR1, TMEM119, P2RY12, CD64, CD68 and MHC-II, compared to those in the caudal regions." (PMID 34311763, 2021).
glioblastoma (7 papers, 2019 to 2024). The most malignant astrocytic tumor (WHO grade IV). "In contrast, P2RY12, a marker of homeostatic microglia, was significantly reduced in the core compared with the infiltrating zone and leading edge (P < 0.05), implying loss of homeostatic microglia in the glioblastoma core." (PMID 37324244, 2023). "In this study, we demonstrate the translatability of microglial-specific genes P2RY12 and TMEM119 in robustly discriminating microglia and TAMs in fluorescently stained human glioblastoma tissue." (PMID 34286275, 2021).
tauopathy (7 papers, 2021 to 2025). Neurodegenerative disorders involving deposition of abnormal tau protein isoforms (tau proteins) in neurons and glial cells in the brain. "Immunostaining confirmed these findings, showing restored expression of the homeostatic microglial marker P2ry12 in Dap12-deficient tauopathy mice." (PMID 41331787, 2025). "To investigate the impact of Dap12 deletion on microglial response to tauopathy, we subclustered microglia expressing microglial hallmark genes Csf1r, P2ry12, and Siglech into four distinct subpopulations based on subcluster marker genes." (PMID 37961627, 2023). "Deletion of APOE4 in astrocytes in a mouse model of tauopathy showed upregulation of homeostatic microglial genes, i.e. P2RY12, downregulation of DAM genes, and decreased synaptic phagocytosis." (PMID 38468308, 2024).
lung carcinoma (6 papers, 2020 to 2025). "Several recent studies have demonstrated that P2RY12 is a favorable factor for long-term prognosis in brain gliomas, lung cancer, and hepatocellular carcinoma." (PMID 40041144, 2025). "And only purinergic receptors P2RX1, P2RX2, P2RX7, P2RY12, P2RY13, and P2RY14 were associated with good prognosis in the lung cancer." (PMID 32638267, 2020). "An increase in the expression of P2RY12, a member of the G protein-coupled receptor family, hinders the proliferation and migration of A549 cells, which is of clinical importance in the realm of lung cancer, particularly lung adenocarcinoma (LUAD)." (PMID 40243586, 2025). "Finally, several genes, such as ADRA2A, P2RY12, ADORA1, CXCR1, and CXCR4, were predicted as potential druggable genes for ALI with GGPPS1-knockout, and were associated with the prognosis of lung cancers." (PMID 35795000, 2022). "However, P2RX1, P2RX7, P2RY12, P2RY13, and P2RY14 were relatively downregulated in lung cancer tissues and were associated with a favourable prognosis." (PMID 33501930, 2021). "However, purinergic receptors P2RX1, P2RX7, P2RY12, P2RY13, and P2RY14 were relatively downregulated in lung cancer tissues and were associated with favorable prognosis." (PMID 32638267, 2020). "These genes are closely related to the proliferation and migration of lung cancer A549 cells, and their downstream targets are regulated by P2RY12, which implies that P2RY12 may affect the progression of non-small cell lung cancer by regulating the expression of these genes." (PMID 40243586, 2025). "We also showed that contrast with the unfavorable prognosis of pyrimidine metabolic rate–limiting enzymes, purinergic receptors P2RX1, P2RX2, P2RX7, P2RY12, P2RY13, and P2RY14 were favorable prognostic markers in patients with lung cancer." (PMID 32638267, 2020). "created a novel Lung cancer prediction model that integrates 5 PyMGs, including P2RX1, P2RX7, P2RY12, P2RY13, and P2RY14, which might be utilized to predict prognosis in Lung cancerpatients." (PMID 37664033, 2023).
status epilepticus (6 papers, 2018 to 2024). Status epilepticus is defined as a continuous seizure lasting more than 30 min, or two or more seizures without full recovery of consciousness between any of them. "Status epilepticus: Increased P2ry2, P2ry4, and P2ry6 and decreased P2ry1, P2ry12, P2ry13, and P2ry14 transcript levels; increased P2Y1, P2Y2, P2Y4, and P2Y6 and decreased P2Y12 protein levels." (PMID 29563872, 2018). "However, in a mouse model of status epilepticus, microglial P2RY12 expression and purinergic signaling were increased in the hippocampus, highlighting the complex dynamics of P2RY12 expression across pathologies." (PMID 38425429, 2024).
amyotrophic lateral sclerosis (5 papers, 2014 to 2023). Amyotrophic lateral sclerosis (ALS) is a neurodegenerative disease characterized by progressive muscular paralysis reflecting degeneration of motor neurons in the primary motor cortex, corticospinal tracts, brainstem and spinal cord. "It was shown that microglia uniformly downregulate their homeostatic signature genes, such as Sall1, Pu.1, Tmem119, Cx3cr1, and P2ry12/13 and upregulate risk genes for AD, such as Apoe and Trem2, in mouse models for aging, AD (5XFAD and APP-PS1), and amyotrophic lateral sclerosis (ALS) (SOD1)." (PMID 30108586, 2018). "Similarly, in the model of amyotrophic lateral sclerosis (ALS) - mSOD1, microglia showed a reduction of the core microglial genes Tmem119 and P2ry12 and upregulated Trem2, Tyrobp, Lpl, and Cst." (PMID 33809675, 2021).
cerebrovascular disease (5 papers, 2018 to 2023). "The purinergic receptor P2RY12 is a clinical target in both cardiovascular and cerebrovascular diseases, since the inhibition of platelet P2RY12 prevents ADP-induced platelet aggregation and thereby reduces the risk of thrombosis." (PMID 32256707, 2020).
experimental autoimmune encephalomyelitis (5 papers, 2017 to 2023). An autoimmune demyelinating disease of the central nervous system that is produced experimentally in animals by the injection of homogenized brain or spinal cord in Freund's adjuvant. "However, in a study investigating experimental autoimmune encephalomyelitis (EAE), an MS model in which pathology is driven mainly by CD4+ T cells, an increased P2RY12 expression was found during the remission phase, which indicates that the regulation of P2RY12 may be more complex." (PMID 30297998, 2018).
Obesity (5 papers, 2014 to 2025). Accumulation of substantial excess body fat. "P2RY13 is highly expressed in spleen, lymph nodes and bone marrow, is structurally related to P2RY12 sharing a high affinity for ADP, and P2RY13-mediated signaling protects against metabolic dysfunctions associated with obesity." (PMID 39995666, 2025).
prion disease (5 papers, 2020 to 2026). A transmissible disease that is caused by a protein that is able to induce abnormal folding of normal cellular proteins, leading to characteristic spongiform brain changes, which are associated with neuronal loss without an inflammatory response. "Interestingly, these findings on the loss of homeostatic microglial proteins in terminal prion disease are in contrast to findings on the RNA expression of the corresponding genes, since P2ry12 RNA expression has been shown to be relatively upregulated." (PMID 36230910, 2022). "In some neurodegenerative diseases, P2RY12 can be associated with activated, inflammatory microglia, but in the context of prion disease, both P2RY12 and TMEM119 are shown to decrease over the course of infection." (PMID 38786054, 2024). "We recently showed that the abundance of homeostatic microglia proteins such as TMEM119 and P2RY12 is significantly reduced in terminal prion disease." (PMID 36230910, 2022).
astrocytoma (4 papers, 2017 to 2019). "P2RY12 is specifically expressed by microglia and associated with ATP-dependent process patrolling and better survival of patients with astrocytoma." (PMID 29286001, 2017). "In this study we observed nuclear localization of P2RY12 in microglial cells in the high-grade tumors, while in the lower graded astrocytomas P2RY12 was expressed in the cytoplasm." (PMID 28073370, 2017).
Thromboembolism (4 papers, 2015 to 2022). The formation of a blood clot inside a blood vessel that subsequently travels through the blood stream from the site where it formed to another location in the body, generally leading to vascular occlusion at the distant site. "Interestingly, an interaction of TTC39A with P2RY12, a receptor involved in platelet aggregation, regarded to be a potential target of thromboembolism treatment, was supposed." (PMID 30496173, 2018).
arterial disease (3 papers, 2020 to 2025). "This may change, as there are reports showing that P2Y12-mediated nucleotide signaling plays a key role in the inflammatory response and that the administration of P2RY12 inhibitors to patients with arterial disease does not increase the risk of cancer." (PMID 35454832, 2022).
bipolar disorder (3 papers, 2021 to 2023). A disorder of the brain that causes unusual shifts in mood, energy, activity levels and the ability to carry out day-to-day tasks. "In bipolar disorder cases that had been prescribed antidepressants, there was reduced expression of FCGR3A, IBA1 and P2RY12 mRNAs and higher expression of HEXB mRNA." (PMID 34911938, 2021).
bleeding disorder (3 papers, 2011 to 2015). "A handful of the candidate defects were present in genes that had previously been associated with platelet bleeding disorders, including P2RY12, VPS33B, GATA1, ANKRD26, HPS1, VWF, and LYST22." (PMID 25556537, 2015).
Cerebral ischemia (3 papers, 2013 to 2021). Restriction of arterial blood supply to the brain associated with insufficient oxygenation to support the metabolic requirements of the tissue. "Webster and collaborators were the first to report the deleterious role of P2RY12 in cerebral ischemia." (PMID 33561958, 2021). "In addition, P2RY12+/- mice or clopidogrel-treated mice subjected to global cerebral ischemia presented less neuronal injury than control mice." (PMID 33561958, 2021).
lung adenocarcinoma (3 papers, 2023 to 2025). A carcinoma that arises from the lung and is characterized by the presence of malignant glandular epithelial cells. "P2RY12, a GPCR activated by adenosine diphosphate, is present in low quantities in lung adenocarcinoma (LUAD) tissues." (PMID 40243586, 2025). "In adenocarcinomas of the lung, Fan and colleagues found a significant correlation between the expression of the purinergic receptor P2Y12 (P2RY12) and the degree of tumor infiltration with immunosuppressive TAMs." (PMID 38275375, 2023).
autoimmune hepatitis (2 papers, 2023 to 2025). Hepatitis caused by autoantibodies. "Regarding existing functional work on P2RY12, our results corroborate studies that found P2RY12 knockout mice are protected from autoimmune hepatitis, and, importantly, had improved blood glucose and less damage to the islets of Langerhans in mice with induced T1D." (PMID 41299435, 2025).
Chediak-Higashi syndrome (2 papers, 2015 to 2025). ChC)diak-Higashi syndrome (CHS) is a rare severe genetic disorder generally characterized by partial oculocutaneous albinism (OCA), severe immunodeficiency, mild bleeding, neurological dysfunction and lymphoproliferative disorder. "For example, defects in LYST are associated with the rare autosomal recessively inherited Chediak–Higashi syndrome, while platelet P2Y12 receptor deficiency is usually due to recessive inheritance of P2RY12 defects." (PMID 25556537, 2015).
colitis (2 papers, 2022 to 2025). Inflammation of the colon. "Our data highlight P2RY12 as a surrogate marker of microglia activation associated with colitis-induced VHS." (PMID 34954381, 2022). "Overall, our work shows that TRPV1+ nociceptor-microglia interactions can precipitate the establishment of persistent visceral pain following colitis, through a central mechanism involving microglial P2RY12." (PMID 34954381, 2022). "Accordingly, blockade of microglial P2RY12 reduced spinal cord neuron activation in the L6-S1 spinal cord sections of colitis mice." (PMID 34954381, 2022). "We next examined whether P2RY12 inhibition prevented microglial activation in the spinal cord during colitis." (PMID 34954381, 2022). "Although DSS-treated mice (both saline- and vehicle-injected groups) exhibited a significant increase in visceromotor response (VMR) to colorectal distension (CRD), pharmacological inhibition of spinal P2RY12 by MRS2395 completely blocked colitis-induced VHS compared with the vehicle-injected group." (PMID 34954381, 2022). "As pharmacological inhibition of P2RY12 was able to prevent both microglial activation and VHS in acute colitis, we hypothesized that P2RY12 activation could prime spinal microglia leading to chronic VHS during the recovery phase of colitis." (PMID 34954381, 2022). "Flow cytometry was performed on brain single cell suspensions to further characterize activated microglia during acute colitis using several markers, including CD45, CD11b, P2RY12, CD11c, CD68, CX3CR1, and LAMP1." (PMID 40457749, 2025). "Collectively, our data provide evidence of a direct TRPV1+ neuron-microglia interaction in colitis pain and suggest that restraining P2RY12 signaling in microglia, via chronic intervention on TRPV1+ neurons, will prevent VHS, despite colitis." (PMID 34954381, 2022). "Importantly, P2RY12 was also upregulated in the spinal cord of DSS-treated mice, suggesting a role of spinal microglial P2RY12 in colitis-induced VHS." (PMID 34954381, 2022). "Therefore, we decided to restrict P2RY12 antagonist administration to the spinal cord, and we used a selective antagonist of P2RY12 receptors, MRS2395, that did not affect the severity of colitis." (PMID 34954381, 2022).
coronary aneurysm (2 papers, 2020 to 2022). Abnormal balloon- or sac-like dilatation in the wall of coronary vessels. "Many studies have shown that the five SNPs (rs9859538 G > A, rs1491974 A > G, rs7637803 C > T, rs6809699 A > C, and rs2046934 G > A) in the P2RY12 gene are associated with aspirin and clopidogrel resistance in heart disease and increases coronary artery aneurysm risk in Kawasaki disease." (PMID 32256707, 2020).
encephalitis (2 papers, 2018 to 2022). An acute inflammatory process affecting the brain parenchyma. "The purinergic receptor, P2RY12, was shown to have a role in the control of viral spread in encephalitis caused by PRV, an alphaherpesvirus that infects the brain via retrograde synaptic spread from peripheral neurons." (PMID 34853891, 2022).
neuroblastoma (2 papers, 2018 to 2021). Neuroblastoma (NB) is the most common solid, extracranial childhood tumor. "P2RY12 pharmacological blockade with ticlopidine and degradation of ADP by APT102 also reduced the TCIPA induced by neuroblastoma and Caco-2 intestinal cells in vitro." (PMID 34589424, 2021).
airway hyperresponsiveness (1 paper, 2022). "The rs8180086, rs3732765, rs10935840, and rs11708767 SNPs of P2RY12, can alter airway hyperresponsiveness in asthmatics exposed to a 1.85 μg/g concentration of house dust mite, whereas the rs7615865 and rs149197 SNPs modified bronchodilator reversibility." (PMID 36292755, 2022).
autoimmune disease (1 paper, 2025). A disorder resulting from loss of function or tissue destruction of an organ or multiple organs, arising from humoral or cellular immune responses of the individual to their own tissue constituents. "Two such examples are VSIR and P2RY12, both of which have existing functional work demonstrating their role in autoimmune disease." (PMID 41299435, 2025).
cognitive deficits (1 paper, 2026). "This elevation in MDK correlates with an increase in activated microglia in the hippocampus and an upregulation of P2ry12 expression, suggesting a potential link between MDK, microglial activation, and cognitive deficits after ischemic renal injury." (PMID 41276912, 2026).